PAUPAR (PAX6 upstream antisense RNA)
Synonyms: DKFZp686K1684; PAX6-AS1
Gene: Long non-coding RNA gene on chromosome 11 (31,812,307 to 32,002,405, forward strand). Ensembl gene ENSG00000281880.
Diseases named in the same sentence as PAUPAR in open-access papers:
PAUPAR is named in the same sentence as 2 diseases in open-access papers, as found by Europe PMC text mining. Sharing a sentence is not in itself a finding about the gene and the disease.
PAUPAR shares sentences with these, for which no sentence is quoted: eye cancer (1 paper); medulloblastoma (1).